PPP2R1A (protein phosphatase 2 scaffold subunit Aalpha)
Description:
The PR65 subunit of protein phosphatase 2A serves as a scaffolding molecule to coordinate the assembly of the catalytic subunit and a variable regulatory B subunit. Upon interaction with GNA12 promotes dephosphorylation of microtubule associated protein TAU/MAPT. Required for proper chromosome segregation and for centromeric localization of SGO1 in mitosis. Together with RACK1 adapter, mediates dephosphorylation of AKT1 at 'Ser-473', preventing AKT1 activation and AKT-mTOR signaling pathway (By similarity). Dephosphorylation of AKT1 is essential for regulatory T-cells (Treg) homeostasis and stability (By similarity). Part of the striatin-interacting phosphatase and kinase (STRIPAK) complexes. STRIPAK complexes have critical roles in protein (de)phosphorylation and are regulators of multiple signaling pathways including Hippo, MAPK, nuclear receptor and cytoskeleton remodeling. Different types of STRIPAK complexes are involved in a variety of biological processes such as cell growth, differentiation, apoptosis, metabolism and immune regulation. Key mediator of a quality checkpoint during transcription elongation as part of the Integrator-PP2A (INTAC) complex. The INTAC complex drives premature transcription termination of transcripts that are unfavorably configured for transcriptional elongation: within the INTAC complex, acts as a scaffolding subunit for PPP2CA, which catalyzes dephosphorylation of the C-terminal domain (CTD) of Pol II subunit POLR2A/RPB1 and SUPT5H/SPT5, thereby preventing transcriptional elongation. Regulates the recruitment of the SKA complex to kinetochores.
Synonyms: PP2Aa; PR65A; PP2A-Aalpha; HJS2; MRD36; PP2AAALPHA
Tractability: Small molecule: a structure with a bound ligand is known; it has a binding pocket of medium quality. Antibody: UniProt places it where antibodies can reach, with high confidence; its Gene Ontology location is reachable by antibodies, with medium confidence. PROTAC: ubiquitination databases record sites on it; its protein half-life has been measured.
Gene: Protein-coding gene on chromosome 19 (52,170,936 to 52,229,518, forward strand). Ensembl gene ENSG00000105568.
Subcellular location: Cytoplasm; Nucleus; Chromosome; Chromosome, centromere; Lateral cell membrane; Cell projection, dendrite
Subcellular location (Human Protein Atlas): Cytosol
Pathways (Reactome):
Cell Cycle: AURKA Activation by TPX2; Amplification of signal from unattached kinetochores via a MAD2 inhibitory signal; Cyclin A/B1/B2 associated events during G2/M transition; Cyclin D associated events in G1; EML4 and NUDC in mitotic spindle formation; Inhibition of replication initiation of damaged DNA by RB1/E2F1; Initiation of Nuclear Envelope (NE) Reformation; Loss of Nlp from mitotic centrosomes; Loss of proteins required for interphase microtubule organization from the centrosome; MASTL Facilitates Mitotic Progression; Mitotic Prometaphase; Recruitment of NuMA to mitotic centrosomes; Recruitment of mitotic centrosome proteins and complexes; Regulation of PLK1 Activity at G2/M Transition; Resolution of Sister Chromatid Cohesion; Separation of Sister Chromatids
Signal Transduction: Beta-catenin phosphorylation cascade; DARPP-32 events; Degradation of beta-catenin by the destruction complex; Disassembly of the destruction complex and recruitment of AXIN to the membrane; ERK/MAPK targets; ERKs are inactivated; Negative regulation of MAPK pathway; PI5P, PP2A and IER3 Regulate PI3K/AKT Signaling; RAF activation; RHO GTPases Activate Formins; Spry regulation of FGF signaling
Disease: APC truncation mutants have impaired AXIN binding; AXIN missense mutants destabilize the destruction complex; CTNNB1 S33 mutants aren't phosphorylated; CTNNB1 S37 mutants aren't phosphorylated; CTNNB1 S45 mutants aren't phosphorylated; CTNNB1 T41 mutants aren't phosphorylated; Signaling by GSK3beta mutants; Truncations of AMER1 destabilize the destruction complex
Immune System: Co-inhibition by CTLA4; Co-stimulation by CD28; PKR-mediated signaling
Metabolism: PP2A-mediated dephosphorylation of key metabolic factors; Regulation of glycolysis by fructose 2,6-bisphosphate metabolism
and 5 more pathways
Gene Ontology:
Molecular function: phosphoprotein phosphatase activity; protein antigen binding; protein binding; protein heterodimerization activity; protein phosphatase regulator activity
Biological process: chromosome segregation; negative regulation of hippo signaling; regulation of transcription elongation by RNA polymerase II; RNA polymerase II transcription initiation surveillance; intracellular signal transduction; meiotic sister chromatid cohesion, centromeric; negative regulation of phosphatidylinositol 3-kinase/protein kinase B signal transduction; protein-containing complex assembly; regulation of cell differentiation; regulation of growth; regulation of hippo signaling; snRNA processing; spindle assembly; T cell homeostasis
Cellular component: chromatin; chromosome; chromosome, centromeric region; extracellular exosome; FAR/SIN/STRIPAK complex; INTAC complex; integrator complex; lateral plasma membrane; neuron projection; neuronal cell body; nucleus; protein phosphatase type 2A complex; protein serine/threonine phosphatase complex; cytosol; membrane; microtubule cytoskeleton; mitochondrion; cytoplasm; dendrite
Genetic constraint (gnomAD): Loss-of-function variants: 15 observed, 67.02 expected, observed/expected ratio (o/e) 0.22, 90% interval 0.15 to 0.34. The upper end of that interval is the gene's LOEUF score, 0.34, which puts it in group 1 of 6, group 1 being the genes least tolerant of losing a copy. Missense variants: 369 observed, 785.44 expected, observed/expected ratio (o/e) 0.47, 90% interval 0.43 to 0.51. Synonymous variants: 337 observed, 332.46 expected, observed/expected ratio (o/e) 1.01, 90% interval 0.93 to 1.11.
Gene-disease validity (ClinGen):
ClinGen rates the evidence that PPP2R1A causes each of these diseases.
complex neurodevelopmental disorder (autosomal dominant): Definitive. A disorder that involves more than one phenotype associated with the central nervous system, including but not limited to intellectual disability, autism, and seizures (epilepsy).
Cancer hallmarks: escaping programmed cell death (promotes); proliferative signalling (promotes); tumour promoting inflammation (suppresses); suppression of growth (promotes); invasion and metastasis (suppresses); invasion and metastasis (promotes)
Homologues: Orthologues: macaque PPP2R1A (100% identical), chimpanzee PPP2R1A (99% identical), mouse Ppp2r1a (99% identical), rat Ppp2r1a (99% identical), pig PPP2R1A (96% identical), dog PPP2R1A (94% identical), tropical clawed frog ppp2r1a (93% identical), rabbit PPP2R1A (92% identical), Drosophila melanogaster Pp2A-29B (75% identical). Paralogues in human: PPP2R1B (86% identical), PPP4R1 (28% identical).
Diseases named in the same sentence as PPP2R1A in open-access papers:
PPP2R1A is named in the same sentence as 104 diseases in open-access papers, as found by Europe PMC text mining. Sharing a sentence is not in itself a finding about the gene and the disease. The quoted sentences say what the papers report.
endometrial cancer (19 papers, 2016 to 2025). Primary or metastatic malignant neoplasm involving the endometrium (mucous membrane that lines the endometrial cavity). "The p.R183W mutation in PPP2R1A is associated with endometrial cancer development and confers increased resistance to clofarabine in uterine serous carcinoma cells through a gain-of-function mechanism." (PMID 40251453, 2025). "Of the common cancer-associated genes, several genes such as PIK3CA, KRAS, FBWX7, and PPP2R1A are frequently mutated in uterine normal endometrium, which is the origin of both endometriosis and endometrial cancer." (PMID 38067342, 2023). "Protein phosphatase 2A gene PPP2R1A mutation P179R is enriched in high-grade endometrial carcinoma; however, in our study it was found in HGSOC case." (PMID 36982928, 2023). "The mutation of PPP2R1A was discovered in many cancers such as endometrial cancer, ovarian and uterine carcinomas, breast cancer, and gastrointestinal stromal tumors." (PMID 36292952, 2022). "Gene mutations in PIK3CA, PIK3R1, KRAS, PTEN, and PPP2R1A commonly detected in type I endometrial cancer cause high activation of the PI3K/Akt/mTOR pathway." (PMID 34831139, 2021). "Gene mutations in PIK3CA, PIK3R1, KRAS, PTEN, and PPP2R1A commonly detected in type I endometrial cancer lead to PI3K/Akt/mTOR pathway activation." (PMID 34831139, 2021). "PPP2R1A mutations are common across ovarian and endometrial carcinomas, although this gene has been found to act as a tumor suppressor or a tumor promoter depending on the cellular context." (PMID 33205120, 2020). "Some studies found that the overexpression or mutation of PPP2R1A in OC and endometrial carcinoma can promote the growth and migration of tumor cells." (PMID 33281878, 2020). "Patient #2 also harbored a mutation encoding the PPP2R1A p.R179 alteration observed in endometrial cancer and endometriosis." (PMID 31857578, 2019). "Of note is the association between somatic PPP2R1A variants with several cancers, such as endometrial cancer and lung cancer, and with some of these variants being identical to those found in the severely affected PPP2R1A subgroup of neurodevelopmental disorders." (PMID 36313552, 2022). "In addition, we show that human endometrial carcinomas with PPP2R1A, SET and CIP2A mutations or changes in mRNA levels are associated with higher mutation burden and MSI status." (PMID 34911954, 2021). "However, the biological role of these mutations of PPP2R1A in ovarian and endometrial cancer progression remains unclear." (PMID 27272709, 2016). "However, the biological role of mutation of PPP2R1A in ovarian and endometrial cancer progression remains unclear." (PMID 27272709, 2016). "The effects of WT and W257G mutant of PPP2R1A were examined in endometrial cancer cell line HEC-251." (PMID 27272709, 2016). "Furthermore, the effects of PPP2R1A overexpression in GC cells differ from its role in promoting the proliferation of ovarian and endometrial cancer cells, as does its ability to inhibit WNK1-induced cell migration in liver cancer cells." (PMID 40251453, 2025). "When PPP2R1A, which is implicated in the negative control of cell growth and division in the same pathway, is concerned in endometrial cancer, it has been correlated with poor survival and serous histology." (PMID 40422510, 2025). "PPP2R1A is a subunit of the serine/threonine phosphatase PP2, which directs PP2 to specific substrates and functions as a tumour suppressor in endometrial cancer." (PMID 37511580, 2023).
endometrial cancer (continued). "Recent studies demonstrate the relevance of PPP2R1A somatic alterations that may contribute to poor prognosis in patients with advance stage endometrial cancer independent of the histological subtype." (PMID 36010253, 2022).
breast carcinoma (12 papers, 2012 to 2025). "In human melanoma, lung cancer, and breast cancer, somatic mutations (an R-to-W change at position 418 [R418W], E64D, and E64G) in PPP2R1A have been identified." (PMID 36094311, 2022). "Several SNPs in PPP2R1A were reported to associated with various cancer risk including breast cancer and uterine serous carcinoma." (PMID 24204789, 2013). "These genetic variants in the PPP2R1A coding region have been consistently associated with several cancers, including breast cancer, lung cancer, melanoma, and colon cancer." (PMID 23555712, 2013). "Women with both the PPP2R1A risk haplotype and a history of proliferative breast disease had an OR of 2.44 (95% CI = 1.7–3.5) for the subsequent development of breast cancer." (PMID 23555712, 2013). "The loss of PPP2R1A protein expression has also been observed in breast cancer." (PMID 23555712, 2013). "Furthermore, a case-control study using haplotype analysis of tagged SNPs in the PPP2R2A (coding for PP2A-Bα) and PPP2R1A (coding for PP2A-Aα) genes demonstrated that certain genotypes were protective for breast cancer, while others modified the risk for women with proliferative breast lesions." (PMID 22539979, 2012). "In our study, we observed a 1.2-fold increase in PPP2R1A levels in the MCF-7 breast cancer cell line treated with propolis compared with untreated cells (p < 0.05)." (PMID 39850502, 2025). "We also identified a cluster associated with the extrinsic apoptotic pathway involving PPP2R1A, PPP2R1B and YWHAE, proteins dysregulated in breast cancer." (PMID 39353922, 2024). "Strikingly, MAP3K1, MAPK11, PPP2R1A, and α2 integrin expression were higher in chemotherapy-resistant tumours in breast cancer patients." (PMID 39666682, 2024). "Consistently, we showed that MAP3K1, MAPK11, PPP2R1A, and α2 integrin expression is higher in chemoresistant breast cancer patients." (PMID 39666682, 2024). "To examine whether regulators of ECM internalisation may impact on chemoresistance in breast cancer patients, we looked at the correlation between MAP3K1, MAPK11, PPP2R1A, and α2 integrin expression and chemotherapy response using transcriptomic data of 3,104 breast cancer patients." (PMID 39666682, 2024). "Reports of somatic mutations of the PPP2R1A and PPP2R1B genes, which encode the α and β isoforms of the structural PP2A/A subunit, were found to be associated with various human cancers, including lung cancer, colon cancer, breast cancer, skin cancer and ovarian cancer." (PMID 26684356, 2016). "In this study, we investigated the effect of propolis on PPP2R1A expression and its relationship with apoptosis in the SW-620 (colorectal cancer), DU-145 and PC-3 (prostate cancer), and MCF-7 (breast cancer) cell lines, with WI-38 (healthy fibroblast) cells serving as the control." (PMID 39850502, 2025). "Second, small-molecule stabilizers targeting the PPP2R1A-PP2Ac complex interface (e.g., DT-061) have demonstrated the potential to restore PP2A’s tumor-suppressing function in various cancer models, including lung and breast cancer." (PMID 41409293, 2025).
ovarian carcinoma (11 papers, 2013 to 2025). A malignant neoplasm originating from the surface ovarian epithelium. "Mutations of PPP2R1A significantly enhance cancer cell migration in endometrial and ovarian carcinomas, whereas allosteric activation of this wild-type complex induces cell cycle arrest with broad anti-tumour activity." (PMID 34728792, 2022). "Studies have found that PPP2R1A has a high-frequency mutation in serous endometrial carcinoma, indicating a poor prognosis, we found that there were more PPP2R1A mutations in ovarian cancer than in other genes." (PMID 33281878, 2020). "PPP2R1A mutants were overexpressed in SKOV3 ovarian carcinoma cells to determine the effect of PPP2R1A mutations on tumor cell growth." (PMID 27272709, 2016). "The RT-qPCR results showed that compared with human ovarian epithelial cells, the expression of B3GAT3, COL5A1, FAM162A, IDUA, and PPP2R1A in ovarian cancer cells was significantly downregulated." (PMID 33281878, 2020). "We further analyzed the differential expression of B3GAT3, COL5A1, FAM162A, IDUA, and PPP2R1A in ovarian cancer SKOV-3 and A2780 cells and HOSEpiC human ovarian epithelial cells." (PMID 33281878, 2020). "PPP2R1A has been identified as a key protein in the subclassifications of both serous endometrial and ovarian carcinomas, as well as clear cell carcinomas of the ovary." (PMID 28250404, 2013). "Endometrioid ovarian carcinomas show broad morphological similarities to their endometrial counterparts with the most common molecular alterations in endometrioid OC including mutations in CTNNB1 (31–53.3%), PIK3CA (15–40%), ARID1A (30%), and PPP2R1A (7–16.6%)." (PMID 41153668, 2025). "Driver mutations in KRAS, PIK3CA, PTEN, PPP2R1A, and ARID1A presented as larger clones than non-driver mutations and with similar frequency in lavages from patients with and without ovarian cancer, indicating prevalent somatic evolution in all patients." (PMID 36311816, 2022).
melanoma (10 papers, 2013 to 2024). A malignant, usually aggressive tumor composed of atypical, neoplastic melanocytes. "Mutations in PPP2R1B and PPP2R1A, the genes for the α and β isoforms of the PP2Aa subunit, have been found in breast and lung carcinomas as well as melanomas." (PMID 38184584, 2024). "Mutations in PPP2R1A frequently occur in cancer, such as lung, breast, and melanoma." (PMID 34837693, 2021). "In this regard, protein phosphatase 2 regulatory subunit A (PPP2R1A), responsible of active interaction between melanoma and lymphatic endothelial cells, has been proposed as a new biomarker in melanoma metastatization." (PMID 34207514, 2021). "Validation experiments showed that the phosphatase 2 regulatory subunit A, α-isoform (PPP2R1A) is expressed on the cell surfaces of both melanoma and LECs in vitro as well as independent melanoma patient samples." (PMID 28036019, 2016). "PPP2R1A facilitates tumor cell–lymphatic endothelial cell interactions during melanoma cell metastasis." (PMID 27023146, 2016). "In summary, for the first time, we demonstrated that PPP2R1A mRNA expression level was elevated in high-grade ovarian serous carcinoma, invasive breast carcinoma, melanoma, lung adenocarcinoma, and bladder carcinoma." (PMID 27272709, 2016). "PPP2R1A-PPP2R1A homodimers occurred at the cellular level to mediate cell–cell interactions at the lymphatic-tumor interface, indicating that PPP2R1A is a new biomarker for melanoma metastasis." (PMID 28036019, 2016).
endometriosis (9 papers, 2018 to 2025). The growth of functional endometrial tissue in anatomic sites outside the uterine body. "Whole-exome sequencing has explored that 79% of patients with deep-infiltrating endometriosis had some harboring oncogenic driver mutations, such as ARID1A, KRAS, PIK3CA, and PPP2R1A." (PMID 34444500, 2021). "Similarly, anatomical subtypes of endometriosis, such as ovarian endometrioma (EN-OV) and deep infiltrating (EN-DI) endometriosis, harbor mutations in PIK3CA, ARID1A, PPP2R1A, and/or KRAS20,21." (PMID 31857578, 2019). "For example, some known somatic driver mutations in the genes ARID1A, PIK3CA, KRAS, and PPP2R1A have been found in the endometriotic lesions of 19 of 24 patients with deep-infiltrating endometriosis even though this form of endometriosis almost never undergoes malignant transformation." (PMID 29945886, 2018). "Next-generation sequencing (NGS) has shown that endometriosis and adenomyosis involve genetic alterations such as KRAS, PIK3CA, PPP2R1A and ARID1A." (PMID 37296736, 2023).